LGALS8 (galectin 8)
Diseases named in the same sentence as LGALS8 in open-access papers (continued):
Sharing a sentence is not in itself a finding about the gene and the disease.
glioma (5 papers, 2016 to 2025). A benign or malignant brain and spinal cord tumor that arises from glial cells (astrocytes, oligodendrocytes, ependymal cells). "Galectin-1 and Galectin-8 have been shown to participate in glioma invasion, and Galectin-1 and Galectin-3 can reportedly promote immunosuppression in glioma microenvironments." (PMID 35814469, 2022). "Galectins 1, -2, -4, -7, -8 and -9 are expressed in human brain and Galectin-1, Galectin-3 (Gal-3) and Galectin-8 (Gal-8) are the most abundantly expressed in human glioma cell lines." (PMID 27459991, 2016). "Therefore, CLEC5A, FMOD, FKBP9, and LGALS8 could be considered crucial prognostic factors in the OS of glioma patients." (PMID 31508371, 2019).
autoimmune uveitis (4 papers, 2015 to 2023). An autoimmune form of uveitis (disease). "Here, we report that treatment with Galectin-8 (Gal-8), a tandem-repeat member of the galectin family, reduces retinal pathology and prevents photoreceptor cell damage in a murine model of experimental autoimmune uveitis." (PMID 26126176, 2015).
multiple myeloma (4 papers, 2020 to 2022). "Moreover, a study analyzed LGALS8 expression in patients with multiple myeloma and found that OS was significantly longer in patients with low LGALS8 levels than in those with high levels." (PMID 34195077, 2021). "Thus, LGALS8 may be an adverse prognostic predictor for multiple myeloma; however, the prognostic implications of its expression remain unclear." (PMID 34195077, 2021).
pancreatic carcinoma (4 papers, 2019 to 2022). "Unpublished, preliminary studies from our group indicates increased Galectin-8 mRNA expression in over 50% of the analysed sample from pancreatic carcinoma patients as compared to normal tissue." (PMID 31861875, 2019). "Galectin-8 is a tandem-repeat Galectin and it is widely expressed in lung and pancreatic carcinoma cells." (PMID 31861875, 2019). "However, Galectin-8 seems to be down-regulated during the progression of pancreatic cancer, as detected in another study using immunohistochemistry." (PMID 31861875, 2019). "siRNA-mediated depletion of Galectin-8 resulted in increased K-Ras4B content and ERK1/2 activity in lung and pancreatic carcinoma cells." (PMID 31861875, 2019).
systemic lupus erythematosus (4 papers, 2015 to 2023). An autoimmune multi-organ disease typically associated with vasculopathy and autoantibody production. "In culture, primary hippocampal neurons secrete Galectin-8, and, in vitro, anti-Galectin-8 auto-antibodies from Systemic Lupus Erythematosus patients affect neuron survival." (PMID 34439592, 2021).
Autoimmunity (3 papers, 2014 to 2025). The occurrence of an immune reaction against the organism's own cells or tissues. "Half of the antigens (Pdhx, Lgals8, and Otud6) have also been associated with inflammation and/or autoimmunity." (PMID 24886063, 2014).
cervical cancer (3 papers, 2022 to 2023). A primary or metastatic malignant neoplasm involving the cervix. "In our study, Galectin-8 and -9 expression were examined in 250 cases of cervical cancer." (PMID 35377045, 2022). "Therefore, in this study, the presence of Galectin-8 and -9 (Gal), both already known as prognostic factors in other tumor entities, were investigated in cervical cancer." (PMID 35377045, 2022). "In this study, we examined Galectin-8 and -9 in cervical cancer samples." (PMID 35377045, 2022). "In contrast, a recent study in patients with cervical cancer revealed that galectin-8 was only expressed in the cytoplasm but not in the nucleus, suggesting that localization of galectin-8 can be localized to a specific compartment, depending of the tumor stage and the cancer type." (PMID 37753083, 2023).
diabetes (3 papers, 2015 to 2023). "However, during diabetes UT-A1 glycan is changed and galectin-8 could bind to UT-A1." (PMID 26483702, 2015).
experimental autoimmune encephalomyelitis (3 papers, 2017 to 2025). An autoimmune demyelinating disease of the central nervous system that is produced experimentally in animals by the injection of homogenized brain or spinal cord in Freund's adjuvant. "Recombinant galectin-8 (Gal-8) ameliorates experimental autoimmune encephalomyelitis (EAE)." (PMID 36607856, 2023).
gastric cancer (3 papers, 2021 to 2025). A primary or metastatic malignant neoplasm involving the stomach. "The reason for the conflict between the oncogenic function and better clinical survival outcome in gastric cancer possibly attributes to the dynamic process of LGALS8 during cancer progression." (PMID 33854625, 2021). "This suggests that galectin-8 may play a tumor-suppressive role in the early stages of gastric cancer by modulating cellular adhesion, immune responses, and intracellular signaling pathways." (PMID 40710343, 2025). "Galectin-8 has emerged as a potential prognostic biomarker in patients with non-metastatic gastric cancer following surgical treatment." (PMID 40710343, 2025).
lung adenocarcinoma (3 papers, 2019 to 2023). A carcinoma that arises from the lung and is characterized by the presence of malignant glandular epithelial cells. "The lung adenocarcinoma cell line H1299 lacks detectable amounts of Galectin-8 and HEK293 kidney cells contain no detectable amounts of the three Galectins and, therefore, were used for ectopic expression experiments." (PMID 31861875, 2019).
osteoarthritis (3 papers, 2018 to 2023). A noninflammatory degenerative joint disease occurring chiefly in older persons, characterized by degeneration of the articular cartilage, hypertrophy of bone at the margins and changes in the synovial membrane. "Galectin-8, a member of the tandem-repeat-type galectins, also mediates cell-cell and cell-matrix interactions and is widely expressed in many organs and tissues under physiological or pathological conditions such as inflamed synovia, osteoarthritis, and tumors." (PMID 34684775, 2021).
acute kidney injury (2 papers, 2025). Sudden and sustained deterioration of the kidney function characterized by decreased glomerular filtration rate, increased serum creatinine or oliguria. "This study provides evidence that endogenous Galectin-8 (Gal-8) mitigates kidney inflammation and fibrosis by reducing the infiltration of Th17 lymphocytes following an acute kidney injury (AKI) episode." (PMID 40375122, 2025).
colon adenocarcinoma (2 papers, 2016 to 2026). "Demonstration on murine colon adenocarcinoma cells identified 3199 proteins with 1669 ± 261 proteins per single cell to characterize galectin-8- and TGF-β-specific responses." (PMID 41740022, 2026).
laryngeal tumor (2 papers, 2013 to 2021). "Galectin-8 may also be involved in angiogenesis, and the expression is changed during hypolaryngeal and laryngeal tumor progression." (PMID 23555683, 2013).
melanoma (2 papers, 2021 to 2025). A malignant, usually aggressive tumor composed of atypical, neoplastic melanocytes. "To further check whether the paxillin clusters formed on galectin-8 substrates contain integrin β3, we used B16 melanoma cells stably expressing GFP-integrin-β3." (PMID 33722978, 2021). "In addition to B16 melanoma cells, we also examined the spreading of several other cell types on galectin-8-coated substrates." (PMID 33722978, 2021). "Both B16 melanoma and HT1080 cells formed more filopodia on galectin-8-coated than on fibronectin-coated substrates." (PMID 33722978, 2021). "However, on fibronectin-coated substrates, B16 melanoma cells formed focal adhesions enriched with GFP-integrin-β3, whereas paxillin-rich clusters formed on galectin-8 did not contain GFP-integrin-β3, and were associated with short actin filaments, rather than with the ends of stress fibers." (PMID 33722978, 2021).
ovarian tumor (2 papers, 2021 to 2024). "However, the underlying functions and mechanisms of LGALS8 expression in ovarian tumors is still unclear and needs further research." (PMID 33854625, 2021). "Similarly, our study validated a lower expression of LGALS8 in ovarian tumor cells and tissues than that in normal cell and tissues at protein level but not at mRNA level." (PMID 33854625, 2021). "It suggests that LGALS8 may influence the prognosis of ovarian tumors at the translation level." (PMID 33854625, 2021).
postmenopausal osteoporosis (2 papers, 2015 to 2021). Metabolic disorder associated with fractures of the femoral neck, vertebrae, and distal forearm. "In this study, we show that mice overexpressing galectin-8, a secreted mammalian lectin of the galectins family, exhibit accelerated osteoclasts activity and bone turnover, which culminates in reduced bone mass, similar to cases of postmenopausal osteoporosis and cancerous osteolysis." (PMID 25955862, 2015).
psoriasis (2 papers, 2024 to 2026). An autoimmune condition characterized by red, well-delineated plaques with silvery scales that are usually on the extensor surfaces and scalp. "When galectin-8 was upregulated, cell proliferation was increased, which resulted in epidermal hyperplasia in psoriasis." (PMID 39337581, 2024).
renal carcinoma (2 papers, 2013 to 2022). A carcinoma arising from the epithelium of the renal parenchyma or the renal pelvis. "The IHC staining results confirmed the correlations between LGALS8, RAB17 and EpCAM and survival of renal carcinoma patients treated with sunitinib, while CD9 failed to achieve significant discriminatory potential." (PMID 23555683, 2013).
serous ovarian cancer (2 papers, 2021). "However, LGALS8 and LGALS13 showed a null association with OS either in endometrioid ovarian cancer or in serous ovarian cancer." (PMID 33854625, 2021).
thyroid cancer (2 papers, 2022 to 2024). "In addition, there is evidence that galectin-8, a soluble lectin expressed in human thyroid carcinomas and other tumor types, binds to 3-O-sulfated galactose residues in glycans, which be involved in various pathways of lymphocyte regulation and stimulation." (PMID 39766189, 2024).
anaplastic large cell lymphoma (1 paper, 2015). Anaplastic large cell lymphoma (ALCL) is a rare and aggressive peripheral T-cell non-Hodgkin lymphoma, belonging to the group of CD30-positive lymphoproliferative disorders, which affects lymph nodes and extranodal sites. "In future investigation Rac1 and Cdc42, which are members of cell motility-regulating proteins will be analyzed in galectin-8-mediated cell invasion in anaplastic large cell lymphoma." (PMID 25573487, 2015). "Neuraminidase from Arthrobacter ureafaciens (AU) treatment resulted in reduction of cell adhesion to galectin-8 in human anaplastic large cell lymphoma (H-ALCL) which was established in our laboratory." (PMID 25573487, 2015).
bladder cancer (1 paper, 2025). "Detection of galectin-8 was significantly lower in invasive bladder tumors compared to superficial bladder cancer or normal urothelium, suggesting that galectin-8 loss is associated with more aggressive bladder cancer phenotypes." (PMID 40252176, 2025). "Interestingly, in contrast to galectin-3 and galectin-1, galectin-8 appears to play an opposing role in bladder cancer progression." (PMID 40252176, 2025).
Corneal opacity (1 paper, 2016). A reduction of corneal clarity. "In contrast, galectin-8 deficiency not only ameliorated corneal opacity but also reduced corneal lymphangiogenesis, suggesting that galectin-8 is involved in the pathogenesis of HSV keratitis, at least partly, by regulating pathological lymphangiogenesis." (PMID 27066737, 2016).
endometrial cancer (1 paper, 2024). Primary or metastatic malignant neoplasm involving the endometrium (mucous membrane that lines the endometrial cavity). "In this study, we examined the intracellular expression of Galectin-8 and -9 by immunohistochemistry in 225 endometrial cancer samples." (PMID 39000016, 2024). "We examined the expression of Galectin-8 and -9 in 225 cases of endometrial cancer." (PMID 39000016, 2024). "Cytosolic Galectin-8 expression is a positive prognostic factor for OS and PFS, while cytosolic presence of Galectin-9 in endometrial cancer is correlated to a better prognosis regarding overall survival." (PMID 39000016, 2024).
endothelial dysfunction (1 paper, 2021). In vascular diseases, endothelial dysfunction is a systemic pathological state of the endothelium (the inner lining of blood vessels) and can be broadly defined as an imbalance between vasodilating and vasoconstricting substances produced by (or acting on) the endothelium. "Separately, our computational predictions and experimental work implicate LGALS8 and GSTP1 as crucial effectors of endothelial dysfunction in PH." (PMID 34669463, 2021).
gastroenteritis (1 paper, 2025). An inflammatory disorder that affects the upper and lower gastrointestinal tract. "In the case of Salmonella, a Gram-negative bacterium associated with food poisoning and gastroenteritis, rupture of the PcV induces the recruitment of LGALS3 (galectin 3) LGALS8 and LGALS9, with LGALS8 playing a unique role as a danger receptor that inhibits bacterial proliferation." (PMID 40910070, 2025).
gynecological cancers (1 paper, 2024). "In gynecological cancers, two galectines are in the focus of research: Galectin-8 and -9, two tandem-repeat galectins." (PMID 39000016, 2024).
HSV keratitis (1 paper, 2016). "Further, in the murine model of herpes simplex virus keratitis, corneal pathology and lymphangiogenesis are ameliorated in Lgals8−/− mice." (PMID 27066737, 2016).
ischemia (1 paper, 2024). A hypoperfusion of the BLOOD through an organ or tissue caused by a PATHOLOGIC CONSTRICTION or obstruction of its BLOOD VESSELS, or an absence of BLOOD CIRCULATION. "It has been discovered that galectin-8 has important functions in the central nervous system, such as protecting neurons from harmful conditions such as ischemia and neurodegenerative diseases." (PMID 39722688, 2024).
kidney damage (1 paper, 2025). "To assess whether endogenous Gal-8 affects the outcome of AKI, we compared parameters associated with kidney damage, including renal function, tubular dilation, and tubular injury markers in Lgals8+/+ and Lgals8−/− mice during the acute phase." (PMID 40375122, 2025). "However, in the Lgals8+/+ mice, tubular dilation and the molecular marker of injury NGAL displayed significantly higher levels, which might initially suggest that Gal-8 negatively influences the early phase of kidney damage." (PMID 40375122, 2025).
lung disease (1 paper, 2021). "Stemming from the known link between hypoxia and inflammatory activation, we reasoned that IBET-762 and LGALS8 may also be relevant to inflammatory pathways activated in hypoxia and thus in group 3 PH due to hypoxic lung disease." (PMID 34669463, 2021).
lung squamous cell carcinoma (1 paper, 2010). "Prior to the knowledge that this antibody was able to specifically bind galectin-8, it was used to detect human lung squamous cell carcinoma by immunoscintigraphy." (PMID 23658855, 2010).
major depressive disorder (1 paper, 2021). An episode of depression lasting two or more weeks without an intervening episode of mania. "Interestingly, the reduction of LGALS8 was disease-specific, as no modulation was observed in the hippocampus from bipolar nor major depressive disorder (MDD) patients." (PMID 34439592, 2021).
malignant lymphoma (1 paper, 2015). "The balance between galectin-1-mediated and galectin-8-mediated adhesion may be associated with movement of lymphoma cells through ECM." (PMID 25573487, 2015). "In the present study desialylation by neuraminidase treatment induced galectin-8-mediated growth inhibition of lymphoma cells." (PMID 25573487, 2015). "Neuraminidase treatment induces growth inhibition of lymphoma cells by galectin-8 (0.5 μM, 7 days)." (PMID 25573487, 2015). "In this report we discuss the fundamental roles of galectin-8 in human malignant lymphoma." (PMID 25573487, 2015). "Neuraminidase treatment induces growth inhibition of lymphoma cells by galectin-8." (PMID 25573487, 2015). "But biological roles of galectin-8 in human malignant lymphoma are not yet fully understood." (PMID 25573487, 2015).
Paget disease (1 paper, 2024). A malignant neoplasm composed of large cells with large nuclei, prominent nucleoli, and abundant pale cytoplasm (Paget cells). "Ultimately, the decrease in nuclei count per osteoclast because of lowered galectin-8 levels, especially its short isoform, suggests the potential influence of galectin-8 on the heightened multinucleation seen in Paget’s disease osteoclasts." (PMID 38395460, 2024).
pneumonia (1 paper, 2021). An acute, acute and chronic, or chronic inflammation focally or diffusely affecting the lung parenchyma, caused by an infection in one or both of the lungs (by bacteria, viruses, fungi, or mycoplasma.). "In pneumonia, the microRNA network controls the replication of human macrophages through LGALS8 and MX1." (PMID 34868310, 2021).
tuberculosis (1 paper, 2021). A chronic, recurrent infection caused by the bacterium Mycobacterium tuberculosis. "Taken together, these data demonstrate that while several galectins are capable of recognizing damaged Mtb-containing phagosomes, galectin-8 plays a privileged role in recruiting downstream autophagy machinery and may represent a promising target for host-directed tuberculosis therapies." (PMID 34225486, 2021).